C1QB (complement C1q B chain)
Diseases named in the same sentence as C1QB in open-access papers (continued):
Sharing a sentence is not in itself a finding about the gene and the disease.
endometrial cancer (1 paper, 2024). Primary or metastatic malignant neoplasm involving the endometrium (mucous membrane that lines the endometrial cavity). "We confirmed by qRT-PCR that the mRNA expression levels of APOE, BGN, BST1, and C1QB in endometrial cancer cell lines (HEC-1B and Ishikawa) were consistent with our previous results." (PMID 39650066, 2024). "The results showed that four hub genes, APOE, BGN, BST2, and C1QB, were abnormally differentially expressed in normal tissues and endometrial cancer." (PMID 39650066, 2024). "In our qRT - PCR verification, the expressions of APOE, BGN, BST1, and C1QB in endometrial cancer cell lines were different from those in normal endometrial epithelial cells, which was consistent with our analysis." (PMID 39650066, 2024). "The four hub genes (APOE, BST1, BGN, C1QB) with differential expression in endometrial cancer tissues may serve as potential therapeutic targets, warranting further research to validate their effectiveness as potential prognostic markers and treatment targets for endometrial cancer." (PMID 39650066, 2024). "The mRNA expression levels of APOE, BST1, and C1QB in endometrial cancer cell lines were significantly higher than those in normal endometrial epithelial cells, whereas BGN expression was higher in normal endometrial cell lines than in endometrial cancer cell lines." (PMID 39650066, 2024).
ependymoma (1 paper, 2023). A WHO grade II, slow growing tumor of children and young adults, usually located intraventricularly. "Finally, proinflammatory microglia with increased expression of the complement cascade genes C1qa, C1qb, C1qb and C4b were observed in a mouse model of the YAP1 gene fusion subtype of pediatric ependymoma." (PMID 37365324, 2023).
glaucoma (1 paper, 2019). Increased pressure in the eyeball due to obstruction of the outflow of aqueous humor. "In the current datasets, optic nerve head monocyte-like cells highly express various complement genes (including C1qa, C1qb, C1qc, C3, and C3ar1), and complement activation is implicated in human glaucoma." (PMID 30670050, 2019).
keloid (1 paper, 2022). An irregularly shaped, elevated mark on the skin caused by deposits of excessive amounts of collagen during wound healing. "Since the downstream genes of RB1 are related with M2 macrophages, for example: C1QC,C1QB,MRC1, fibroblasts in keloid may be beneficial for the transition and proliferation of M2 macrophages." (PMID 35990663, 2022).
kidney damage (1 paper, 2023). "In our study, C1QB was also strongly associated with kidney damage." (PMID 38028597, 2023).
myocardial infarct (1 paper, 2024). "These include C1qa, C1qb, and C1qc, all components of the membrane attack complex, as well as C5ar1, the receptor for the complement anaphylatoxin 5a, which can stimulate immune cells in myocardial infarct models." (PMID 39202335, 2024).
nasal polyps (1 paper, 2022). "C1QA and C1QB are the components of complement C1q, the expression of which was significantly increased in nasal polyps according to a previous study." (PMID 36466903, 2022).
periodontitis (1 paper, 2024). An acute or chronic inflammatory process that affects the tissues that surround and support the teeth. "In our study, C1QB exists in the core ceRNA network in periodontitis differential mRNAs and differential lncRNAs, which can be seen in the existing studies indicating that C1QB and C1QA have a strong reciprocal relationship." (PMID 38919957, 2024).
PFAPA syndrome (1 paper, 2013). An auto inflammatory syndrome characterized by recurrent febrile episodes associated with aphthous stomatitis, pharyngitis and cervical adenitis. "In PFAPA syndrome, expression of complement-related genes, such as C1QB and IL-1-related genes, and genes induced by IFN-γ also increase during episodes of fever." (PMID 22940910, 2013).
Pleural effusion (1 paper, 2023). The presence of an excessive amount of fluid in the pleural cavity. "Among the top 10 genes, CARD-17, GBP2, and C1QB expressed in PF showed an above 80% accuracy rate in discriminating PlTB from other causes of pleural effusion." (PMID 38288122, 2023).
pulmonary tuberculosis (1 paper, 2023). A bacterial infection that affects the lungs and is caused by Mycobacterium tuberculosis. "Based on a reanalytical methodology by bioinformatics that utilizes a previously published transcriptomic public dataset in pulmonary tuberculosis, we succeeded in validating a total of three candidates, CARD17, GBP2, and C1QB genes, in clinical specimens." (PMID 38288122, 2023).
retinoschisis (1 paper, 2017). An inherited or acquired disorder characterized by splitting of the retina into two layers. "It is noteworthy to mention that retinoschisin knock out mouse retina displayed upregulation of C1qb and MAP Erk1/2 kinases indicating the involvement of complement activation in retinoschisis." (PMID 28450823, 2017).
sarcopenia (1 paper, 2025). Progressive decline in muscle mass due to aging which results in decreased functional capacity of muscles. "In both test datasets (GSE149331 and GSE8479), the expression of CLIC5 and SLC38A1 was significantly downregulated in AP and sarcopenia, while the expression of C1QB was significantly upregulated." (PMID 40785039, 2025). "The diagnostic value of CLIC5, SLC38A1 and C1QB was performed by receiver operating characteristic curves and the area under the curve in the datasets, and the validation results confirmed a consistent trend of downregulation of CLIC5 and SLC38A1 in AP and sarcopenia." (PMID 40785039, 2025).
steatosis (1 paper, 2022). Increased lipid within the cytoplasm of cells. "The expression of C1qa, C1qb, C1qc, and C2 in KCs was significantly higher in patients with severe steatosis when compared to healthy controls." (PMID 36304458, 2022). "KCs in healthy and steatosis patients highly expressed C1qa, C1qb, C1qc, and ApoE transcripts." (PMID 36304458, 2022).
type 2 diabetes (1 paper, 2018). "Recently, of eight candidate biomarkers studied after adjustment for clinical predictors, apolipoprotein A4 (ApoA4), CD5 antigen-like (CD5L), and complement C1q subcomponent subunit B (C1QB) independently predicted rapid decline in eGFR in 345 people with type 2 diabetes." (PMID 29520581, 2018).
ulcerative colitis (1 paper, 2024). An inflammatory bowel disease involving the mucosal surface of the large intestine and rectum. "Interestingly, APOE, C1QB, and matrix metalloproteinase 12 (MMP12) are highly expressed in C1QB+ macrophages, IL-1B+ macrophages and CALD1+ macrophages from ulcerative colitis patients." (PMID 39095853, 2024). "Moreover, we also portrayed 5 subpopulations of monocytes, C1QB+ macrophages, CALD1+ macrophages, IL-1B+ macrophages, and SERPINA1+ macrophages in the intestinal mucosa from ulcerative colitis patients." (PMID 39095853, 2024).
tumor (69 papers, 2011 to 2026). "Intriguingly, the C1QB+ macrophages exhibited lowest M1_score and highest M2_score, thereby being deemed as tumour‐associated macrophages (TAMs)." (PMID 39422697, 2024). "Within the macrophages, we identified two clusters of tumor-associated macrophages (TAMs; Fcgr2b+, Ccl4+, Trem2+) and one enriched in complement genes (C4b+, Cfp+, C1qb+)." (PMID 38570533, 2024). "Among macrophages, most cells expressed high levels of complement (C1qa, C1qb, C1qc), which in tumor-associated macrophages have been reported to correlate with immune exhaustion and poor survival." (PMID 36433954, 2022). "Cells in Mac_0 were characterized by expression of complement-related genes (C1qa, C1qb, C1qc) and cytokines (Spp1, Ccl12), while cells in Mac_1 expressed higher levels of several tumor-associated macrophage-related genes such as Arg1, Cebpb, and Ier3." (PMID 34030676, 2021). "In the present study, we found significantly higher expression of C1QB, that encodes the C1qB chain, in tumor than adjacent normal GC tissues." (PMID 33014868, 2020). "MФ‐C1q expresses C1QA, C1QB and in either tumours or normal tissues, complement C1q is the marker of immunosuppressive macrophages." (PMID 39968688, 2025). "Except for M09, all other subtypes expressed macrophage markers such as CD68, C1QB, S100A9, and AIF1, suggesting that they are tumor-associated macrophages (TAMs)." (PMID 40260248, 2025). "Complement components C1qA, C1qB, and C1qC were significantly increased in tumor-bearing mice that had been irradiated, whereas similarly aged mice without tumors displayed a decline in complement system activity." (PMID 40757647, 2025). "C1q is synthesized in the tumor microenvironment and functions as an extracellular matrix protein, and C1QB is a component of C1q." (PMID 38980810, 2024). "Recent evidence suggested that C1qA, C1qB, C1qC positively influence anti-tumor through antibody-mediated immune responses." (PMID 39232806, 2024). "Taken together, the ratio between CD8A and either C1QA, C1QB or C1QC in bulk tumour gene expression data is prognostic in at least five tumour types." (PMID 36724681, 2023). "The hyperexpanded and large TCR types mainly existed in C1qb+ and especially Fscn1+ macrophages, which mainly existed in tumor tissues." (PMID 36718369, 2023). "Immune and stromal cell populations included 2 populations: Macrophages 1 (c1: C1qa, C1qb, C3aR1, Cd68, Csf1r, Tlr2, and Cd86) and 2 (c6 + c9: Ccr7, Csf2rb, Il1b, and Cd74) expanded in PNs as a percentage of total tumor cells." (PMID 36134665, 2022). "Similar to the SAMs, the TAMs in the primary tumor separated into two populations: one with high expression of Chil3, Plac8, and Ly6c2 (Chil-TAMs), and the other with high expression of C1qa, C1qb, and Trem2 (Cq-TAMs)." (PMID 33782087, 2021). "Compared with other immune cells, the macrophages in the primary tumor (i.e., TAMs) exclusively exhibited high expression of the SAMs signature genes (Chil3, Trem2, C1qa, and C1qb), whereas Plac8 and Ly6c2 were broadly expressed across cell types." (PMID 33782087, 2021). "Taken together, we detected an increase in Cq-TAMs and an increase in the expression of Chil3, Trem2, C1qa, and C1qb in the tumor compared with the normal pancreas." (PMID 33782087, 2021). "TYROBP and C1QB were mainly located in tumor cells, which needed further validation in the experiments." (PMID 33014868, 2020). "Macrophages in HCC are tumor associated macrophages (TAMs), based on marker genes C1QA, C1QB, co-express M1, and M2 signals (e.g. M1:CD64, M2: MACRO)." (PMID 33224891, 2020). "Vcam1 and C1qb were undetectable in both tumor epithelia and PBMC but readily detected in whole tumors, suggesting expression in other cell lineages/biological contexts such as endothelium/ coagulation." (PMID 28632792, 2017). "In addition, the up-regulation of C1qb, C1qa, Lamp1, Lgals3, Gm2a, Gusb, Bax, and other genes helps to enhance the anti-tumor and anti-infection ability of the immune system." (PMID 40767963, 2025).
tumor (continued). "Bulk analysis of PNF macrophages revealed a mixed M1 (anti-tumor)/M2 (pro-tumorigenic) RNA signature, and single cell analysis revealed a subpopulation marked by CC1qa, C1qb, and C1qc, previously identified in tumor-promoting macrophages correlating with T-cell exhaustion." (PMID 38458648, 2024). "Furthermore, APOE, APOC1, C1QA, C1QB, and NUPR1 are indicative markers of variations in the infiltration of tumor-associated macrophages (TAM), where TAM infiltration is known to be associated with unfavorable survival outcomes in solid tumors." (PMID 38783355, 2024). "VCAN, CD3G, and C1QB were three key genes that influenced the tumor purity of DLBCL, and could also exert certain impact on drug sensitivity and prognosis of DLBCL patients." (PMID 38980810, 2024). "Notably, the expression levels of APOE, BGN, C1QB, and BST2 were found to correlate with cancer genomic atlas data, and were implicated in tumor immune infiltration." (PMID 39650066, 2024). "We observed that tumor-associated macrophages highly expressing C1QC, C1QA, and C1QB could be identified as C1QC + macrophages." (PMID 37344903, 2023). "Ifitm6+, Hcar2+, Retnla+, Spp1+, C1qb+, and Fscn1+ macrophages mainly existed in tumor tissues." (PMID 36718369, 2023). "In addition, multiple components of the complement system, a central mediator of RT-induced tumor-specific immunity, were upregulated — specifically, C1qa, C1qb, C1ra, C1s1, C3, C3ar1, C4b, and C6." (PMID 37345658, 2023). "We found that the mRNA expression of C1QA, C1QB, C1QC, C5AR1, C3AR1, C1QR (CD93), CR1, CR2, CR3 (ITGAM), and CR4 (ITGAX) were positively associated with almost all kinds of tumor immune cells, including CD8+ T cells, CD4+ T cells, B cells, macrophages, monocytes and DCs." (PMID 34813686, 2022). "In general, we observed APOC1, APOE, C1QB and NURP1, which may reflect differential abundance of tumor-associated infiltration of macrophages (TAM)." (PMID 36250636, 2022). "Similarly, analysis of macrophages from the 3 states revealed that there were distinct genes in the Tumor macrophages which includes genes like Cotl1, Tgfbi, Fos, and Fn1 along with complement activation genes C1qa, C1qb, and C1qc." (PMID 35851387, 2022). "Prior work has shown how sub-units of the C1Q complex, including C1QA, C1QB, and C1QC, are associated with modulating the local environment of tumor cells and may therefore reflect local microenvironment remodeling after brain injury." (PMID 36670596, 2022). "Having identified Chil3, Trem2, and the complement genes, C1qa and C1qb as markers of SAMs in tumor-bearing mice, we next investigated whether these macrophage subsets also exist in primary tumors." (PMID 33782087, 2021). "Therefore, C1qA, C1qB and C1qC differential expression is closely related to the degree of tumor necrosis, plays a role in inhibiting tumor development to a certain extent." (PMID 34079754, 2021). "For example, genes related to the GO term “components of complement,” such as C1QA, C1QB, and C7, may promote tumorigenesis in cells within the tumor microenvironment." (PMID 34557425, 2021). "In addition, the high expression of TYROBP and C1QB were also validated in the GC tumor tissues compared with the adjacent mucosa tissues using the ZJU cohort (PTYROBP = 0.045, PC1QB = 0.031)." (PMID 33014868, 2020). "Based on these findings, we propose that C1QB in DLBCL might share similarities with its functions in other tumor types, particularly regarding the promotion of recruitment and subsequent deactivation of CD8 + T cells within the TME through the induction of immune checkpoint effects." (PMID 38980810, 2024). "Among potential eat-me signals, we found significant overexpression of C1Q complement components C1qa, C1qb, and C1qc, which have been shown to decorate the surface of apoptotic cells to target them for phagocytosis, and of Slamf7, which is involved in phagocytosis of hematopoietic tumor cells." (PMID 36240276, 2022).
tumor (continued). "In addition, tumor-bearing SAMs displayed a high expression of complement C1q A chain and B chain (C1qa and C1qb) and triggering receptor expressed on myeloid cells 2 (Trem2), and a low expression of the major histocompatibility complexes (Cd74, H2-D1, H2-Aa, and H2-Eb1) compared with control SAMs." (PMID 33782087, 2021). "Our analyses revealed that CXCL9+ macrophage-rich immune cell niches were accumulated in the tumor-liver invasive margin, where 2 subclasses of the CXCL9+ immune cell niches, CXCL9+TRAC+ (CT) and CXCL9+C1QB+ (CC) niches, were identified." (PMID 41766656, 2026). "Taken together, our findings underscore the significant roles of VCAN, CD3G, and C1QB, which influence both the TME and the behavior of tumor cells." (PMID 38980810, 2024). "We developed a novel immunohistochemical panel to assess prognostic outcomes and treatment sensitivity by detecting the expression of VCAN, CD3G, C1QB, CD68, CD4, and CD8 in both the TME and tumor cells of 190 DLBCL patients." (PMID 38980810, 2024). "We also observed depletion of sgRNAs targeting genes with known function in tumor immunity and/or resistance to immune-checkpoint therapy, such as CD4, C1qb in KrasG12D lungs." (PMID 37258521, 2023). "Comparison of the gene expression of TREM2+ TAMs between the tumor and adjacent normal tissue revealed that TREM2, SPP1, APOE, C1QA, C1QB, and C1QC were upregulated in tumors, which was consistent with the results for GSE160269." (PMID 37187751, 2023). "TAMs and CAFs were classified according to their tumor origin and high expression of SPP1, C1QB, IL1B, S100A8, S100A9 and type I collagens (COL1A1 and COL1A2)." (PMID 36209225, 2022). "The CIBERSORT algorithm was applied to analyze the proportions of tumor-infiltrating immune subsets to further confirm the correlations between the TME and C1qA, C1qB, and C1qC expression levels." (PMID 34079754, 2021). "We then analyzed single-cell RNA sequencing data from patient tumors and novel single-cell RNA sequencing data from liver metastases and identified macrophages expressing high levels of C1QA, C1QB, and TREM2 in both primary tumor and metastases." (PMID 33782087, 2021). "Similar to our scaffold and primary tumor data, the macrophages in the liver metastases had high expression of C1QA, C1QB, and TREM2 consistent with this macrophage population being part of a systemic response to a primary tumor." (PMID 33782087, 2021). "The levels of eight genes (SPI1, RNASE6, C1QB, C1QC, CSF1R, C1QA, TBC1D2, and ATP6V0E1) expression were higher in tumor samples from UALCAN." (PMID 32038997, 2019). "However, the function of C1QB in tumor biology and tumor immunology is still largely unknown." (PMID 21698244, 2011). "The MFP proteome was enriched for several immune-related and plasma proteins more indicative of inflammatory infiltration and chronic immune activation rather than tumor-specific remodeling including C1QB, CFH, MZB1, IGKV3-20, ORM2, ALB, and AZGP1." (PMID 41007761, 2025). "Based on these results, we can speculate that C1QA, C1QB, and C1QC play key roles in immune cell infiltration in the tumour microenvironment of SKCM." (PMID 36110204, 2022). "The transcription levels of C1QA, C1QB, and C1QC were analysed based on pan-cancer data in GEPIA to observe whether there were significant differences in their expression among common tumour types." (PMID 36110204, 2022). "Therefore, we speculated that the high expression of C1QA, C1QB, and C1QC may play a dual regulatory role through anti-tumour immunity and the induction of cancer cell apoptosis." (PMID 36110204, 2022). "Thus, we infer that genetic variation in the C1QB may affect tissue infiltration and C1q secretion of peripheral blood monocytes, as well as the function of C1q interacting with different receptors that can influence CRC tumor progression." (PMID 39109334, 2024).
tumor (continued). "Significantly reduced C1qa expression, but not C1qb and C1qc expression, was observed in both MPE and tumor tissue of KO mice, indicating effective C1qa disruption in C1qa-/- mice." (PMID 39664577, 2024). "Although these results are encouraging, the tumour immune infiltration relationship between C1QA, C1QB, C1QC, and SKCM has not been established, and the expression, mechanism of action, and prognostic significance of complement components in SKCM require further exploration." (PMID 36110204, 2022).